DHX36 (DEAH-box helicase 36)
Diseases named in the same sentence as DHX36 in open-access papers (continued):
Sharing a sentence is not in itself a finding about the gene and the disease.
pneumonia (1 paper, 2017). An acute, acute and chronic, or chronic inflammation focally or diffusely affecting the lung parenchyma, caused by an infection in one or both of the lungs (by bacteria, viruses, fungi, or mycoplasma.). "Thus, both DDX19a-NLRP3-related viral RNA sensing and DHX36-mediated viral N protein recognition might contribute collaboratively to uncontrolled progression of virus-induced inflammation, which culminates in exacerbated pathogenesis and development of pneumonia." (PMID 29123520, 2017).
tumor (11 papers, 2015 to 2025). "Nevertheless, DHX36 is implicated as a regulating factor in breast cancer tumor suppression, and is positively associated with increased patient survival." (PMID 34862880, 2021). "Interestingly, we also identify the effect of DHX36 on tumour cell susceptibility to chemotherapeutic drugs, which imply its therapeutic potential." (PMID 33987090, 2021). "In the LUSC subset, gene expression of DHX36 was higher in the tumour group (n=502) than in normal tissues (n=51) (p<0.0001), which was similar to the pattern before subtype classification." (PMID 33987090, 2021). "We also compared the gene expression of DHX36 among different Tumour-Node-Metastasis (TNM) staging types." (PMID 33987090, 2021). "In contrast, our data suggest that DHX36 is a tumour suppressor based on a variety of cellular assays." (PMID 33987090, 2021). "Using a xenograft tumor model in mice, researchers showed that lentiviral knockdown of DHX36 increases tumor growth and cancer cell invasion, with a concurrent reduction of cellular apoptosis." (PMID 34862880, 2021). "In the LUAD subtype, there was a significant difference in the DHX36 gene expression level between tumour (n=515) and normal tissue (n=59) groups." (PMID 33987090, 2021). "The stable lentiviral knockdown of the DHX36 allows us to determine the role of DHX36 as a tumour suppressor through a variety of cellular and molecular assays including migration, ECIS, 3D tumour model and single-cell colony formation." (PMID 33987090, 2021). "In all NSCLC samples, gene expression of DHX36 was higher in the tumour group (n=1017) than in normal tissues (n=110) (p<0.0001)." (PMID 33987090, 2021). "We fabricated 3D lung cell spheroids to understand the tumour growth and change of viability mediated by the knockdown of DHX36." (PMID 33987090, 2021). "This demonstrates that DHX36 is indeed a multifunctional protein and its role in the stress process in tumour cells." (PMID 33987090, 2021). "RNA helicase associated with AU-rich element (DHX36) knockdown resulted in significant increases in PTX1 protein levels, a transcription factor, with roles in development and as a tumor-suppressor." (PMID 33499187, 2021). "Therefore, at least in some cancers, DHX36 may function as a tumor suppressor." (PMID 34862880, 2021). "That DHX36 and DHX9 are overexpressed in cancer tissues supports the proposed role of RNA helicases in tumor initiation, progression and maintenance." (PMID 30591072, 2018). "Although the TCGA dataset shows higher expression of DHX36 gene in tumour tissue, which is in line with the altered protein levels in a CPTAC dataset, there are also other studies showing that the transcript level of DHX36 is lower in the tumour samples." (PMID 33987090, 2021). "The other tested DNA sensors (Rig-I, Cgas, Sting, Ddx41, Dhx9, Dhx36, Lrrfip1, Mre11) were expressed in the tumor cells but were not significantly upregulated after irradiation." (PMID 33202881, 2020).
cancer (10 papers, 2015 to 2025). A tumor composed of atypical neoplastic, often pleomorphic cells that invade other tissues. "Here, we describe the role of the DHX36 in modulating transcription in an immortalized human T lymphocyte Jurkat cancer cell line using RNA sequencing (RNA-seq) by exploring the functional consequences of gene dysregulation related to the loss of DHX36 with bioinformatic analyses." (PMID 38339029, 2024). "Genes that significantly change their expression, particularly those that show a significant increase in RNA abundance under DHX36 knockout, are associated with a range of cellular functions and processes, including numerous transcription factors and oncogenes, and are linked to several cancers." (PMID 38339029, 2024). "These cancer associations were for genes that were upregulated in DHX36 KO cells, which included many oncogenes in which G4 stability may be enhanced, indicating that DHX36 activity could typically act to suppress their expression under normal conditions." (PMID 38339029, 2024). "Our work highlights the direct and indirect role of DHX36 in the transcriptome of T-lymphocyte leukemia cells and the potential for DHX36 dysregulation in cancer." (PMID 38339029, 2024). "G4 structures and DHX36 interactivity has been studied in relation to cancer and tumorigenesis, neurodegenerative diseases and aging mechanisms including cellular senescence." (PMID 36376304, 2022). "Overall, DHX36 plays substantial roles in some forms of cancer, with multiple mechanisms related to tumorigenesis." (PMID 34862880, 2021). "Though much attention has been given to the G4 structures and DHX36 interactivity in cancer tumorigenesis and viral pathology mechanisms, important questions have yet to be answered about their role in neurodegenerative diseases and aging." (PMID 34862880, 2021). "The functions of DHX36 in cellular homeostasis have been extensively studied, particularly in the areas of cancer, telomere maintenance, and antiviral immune response." (PMID 34862880, 2021). "Among them, the expression of AIM2/ASC/IL-18, MyD88, DAI, DHX36, and DDX60 were associated with cancer stages." (PMID 31949493, 2020). "When comparing the expression levels of the helicases across normal tissue and tumors, recovered from the GENT database, we found that DHX36 displayed altered expression levels in eight and DHX9 in nine out of 15 types of cancers analyzed." (PMID 30591072, 2018). "The clinical significance and role of DHX36 in cancer are poorly understood, regardless of enormous indirect clues and a few highly specific studies." (PMID 33987090, 2021). "The expression of DHX36 in CRC was not different in our clinical samples or AOM/DSS-treated samples, but increased in ATCG database and was associated with cancer stages." (PMID 31949493, 2020). "Recent studies suggest that DNA sensors such as AIM2, TLR9, DHX9, DHX36 and adaptor STING may have roles in CRC development, and the other DNA sensors such as DDX41, DDX60, IFI16, and DAI participate in the development of other types of cancers." (PMID 31949493, 2020).
infection (4 papers, 2014 to 2025). The state of being infected such as from the introduction of a foreign agent such as serum, vaccine, antigenic substance or organism. "DHX36 is normally distributed diffusely in both the nucleus and cytoplasm; however, IAVΔNS1 infection induced its re-localization to speckles, which co-localized with RIG-I and TIAR." (PMID 24651521, 2014). "While these DEAD/H‐box helicases associate with RLRs in response to infection, DHX36 is unique in that it has been identified to associate with the C terminal domain (CTD) of RIG‐I in resting cells in the absence of infection." (PMID 39620586, 2025). "However, at 24 h post infection, augmented cell death was observed in DHX36 KO cells compared to WT cells." (PMID 24651521, 2014). "We observed that DHX36 augments signaling by RIG-I in a stimulus-dependent manner: signaling induced by infection with IAVΔNS1, NDV and transfection of pIC is enhanced by DHX36." (PMID 24651521, 2014). "The net impact of DDX21 during infection likely depends on virus‐ and cell‐type‐specific factors such as the activation of caspases and the expression of other helicases like RIG‐I, DDX1, and DHX36." (PMID 39620586, 2025). "IFN-ß induction by infection with influenza A virus (IAV) ΔNS1, Newcastle disease virus (NDV) or by transfection of poly rI: poly rC (pIC) was significantly reduced in the absence of DHX36 as revealed by quantification of IFN-ß protein and mRNA." (PMID 24651521, 2014).
neurodegenerative disease (3 papers, 2021 to 2022). A disorder of the central nervous system characterized by gradual and progressive loss of neural tissue and neurologic function. "We then discuss the role of DHX36 in neurodegenerative diseases and brain aging and highlight possible future directions for research in these areas." (PMID 34862880, 2021). "Is there any indirect evidence that DHX36 is involved in neurological or neurodegenerative diseases?" (PMID 34862880, 2021). "Thus, dysfunctional DHX36 may lead to neurological and neurodegenerative diseases, which remains to be elucidated." (PMID 34862880, 2021).
DHX36 also shares sentences with these, for which no sentence is quoted: heart failure (2 papers); tuberculosis (2); autoimmune thyroid disease (1); Azoospermia (1); Cognitive impairment (1); colon adenocarcinoma (1); fragile X-associated tremor/ataxia syndrome (1); frontotemporal dementia (1); graft versus host disease (1); lung disease (1).